MYC (MYC proto-oncogene, bHLH transcription factor)
Diseases named in the same sentence as MYC in open-access papers (continued):
Sharing a sentence is not in itself a finding about the gene and the disease.
medulloblastoma (continued). "Group 3 tumors account for 28% of all medulloblastomas, and conceptually it may be convenient to consider them as being associated with MYC amplification (not MYCN) but not exclusively." (PMID 25101241, 2014). "Therefore we examined the expression of c-MYC in JQ1 treated medulloblastoma cells." (PMID 24796395, 2014). "Therefore, ID3 may represent the metastatic/ aggressive phenotype of Group 4 medulloblastomas that lack MYC amplification." (PMID 23768125, 2013). "With the aim of exploring molecular targeted therapeutic options for high-risk medulloblastomas, we analyzed whether inhibiting BET bromodomain proteins, and thereby targeting MYC and its target genes, could be effective against preclinical models of medulloblastoma." (PMID 24231268, 2013). "Thus, OTX2 seems to have a functional interaction with MYC, which might explain why both genes are frequently co-expressed at high levels in medulloblastoma." (PMID 22016811, 2011). "Combination therapy targeting MYC (by BET inhibition) and mTOR signaling proved efficacious against medulloblastoma." (PMID 39779613, 2025). "Through R2 Genomics Analysis and Visualization Platform data mining (Mixed Medulloblastoma Public Pomeroy 204 MAS 5.0-u133a), MYC was found to be closely related to the cell cycle in addition to conventional transcriptional regulation and RNA metabolism." (PMID 40229260, 2025). "All malignant cells expressed moderate to high levels of both c-MYC and PA2G4, except the medulloblastoma cell line, UW228." (PMID 41002386, 2025). "Interestingly, group 3/4 medulloblastomas with amplification of MYC or MYCN or duplicated SNCAIP had significantly higher SNV densities at both ECA and MRCA than the remaining tumours, suggesting that later onset of (pre-)malignancy may predispose to the subsequent acquisition of these drivers." (PMID 40335697, 2025). "(2020) investigated the interaction between MYC and HDAC2 and reported that HDAC inhibition disrupts the MYC-HDAC2 complex in MYC-amplified medulloblastoma, leading to reduced chromatin binding of MYC." (PMID 40556679, 2025). "So, in order to simultaneously target MYC, mTOR/PI3K, and cyclin pathways, a combination of ribociclib was tested with BET-bromodomain JQ1 and paxalisib on group 3 medulloblastoma cell lines." (PMID 40862786, 2025). "In vivo studies revealed that the overexpression of the Gfi1 + c-MYC (GM) and Otx2 + c-MYC (OM) genes produced group 3 medulloblastoma." (PMID 39062993, 2024). "In the case of medulloblastoma, OTX‐2 and MYC were shown to bind tightly to each other in the transcription start sites of genes that contribute to the cancer phenotype." (PMID 38925618, 2024). "This work holds the promise of significantly advancing our understanding of MYC-driven oncogenesis and provides critical preclinical data essential for the development of novel therapies targeting CDK8 and mTOR in MYC-driven medulloblastoma." (PMID 39574899, 2024). "For example, treating medulloblastoma cell lines with JQ1 significantly decreased cell proliferation and preferentially induced apoptosis in MYC-overexpressed cells." (PMID 39273015, 2024). "For example, a medulloblastoma organoid model was established by overexpressing OTX2 and MYC in human cerebellar organoids to replicate the features of medulloblastoma group 3 tumors." (PMID 38353122, 2024). "Knockdown of PRMT5 in medulloblastoma cells suppresses cell growth by diminishing MYC stability, supporting the functional role of the PRMT5–MYC interaction complex in medulloblastoma." (PMID 38136401, 2023). "In medulloblastoma, treatment with SMO inhibitor, GDC0449, showed a decrease in the c-MYC RNA expression and protein levels." (PMID 34642915, 2022). "MYC-amplified D425MED and MED211 medulloblastoma orthotopic xenograft brain tumors upregulated nucleotide, hexosamine, amino acid and glutathione synthesis compared to normal brain." (PMID 35267619, 2022).
medulloblastoma (continued). "Metabolic analysis found 3000–4000 analytes in normal brain (normal cortex and contralateral and uninvolved cerebellum) and orthotopic MYC-amplified D425MED and MED211 medulloblastoma tumors." (PMID 35267619, 2022). "The modalities for molecular stratification of medulloblastoma vary from institution to institution, with a combination of immunohistochemical stains (beta‐catenin, GLI2, YAP1) and FISH (MYC amplification) being most utilized." (PMID 35266242, 2022). "Together, these data indicated that FBXW7 physically interacts with PLK1 and c-MYC, and it induces the ubiquitination and proteasome degradation of PLK1 and c-MYC in medulloblastoma." (PMID 33494392, 2021). "Chromothripsis in medulloblastoma leads to recurrent translocations that eventually fuse a lncRNA PVT1 to MYC, resulting in a continuous oncogenic effect via MYC amplification." (PMID 33557176, 2021). "Microarray results showed that the expression of c-MYC and PLK1 was positively correlated in medulloblastoma." (PMID 33494392, 2021). "We then evaluated the expression of MYC, PLK1, and FBXW7 in a panel of well-characterized medulloblastoma cell lines." (PMID 33494392, 2021). "Altogether, these findings demonstrated that PLK1 inhibition stabilizes FBXW7 in MYC-driven MB, thus revealing an important function of FBXW7 in suppressing medulloblastoma progression." (PMID 33494392, 2021). "MYC, EZH2 and SOX9 are known to be repressed in response to BET inhibition in several malignancies, such as medulloblastoma, bladder cancer and myelofibrosis, but as yet the effect of JQ1 on these genes in TNBC has not been explored." (PMID 32166583, 2020). "Silencing of PRMT5 in MYCN‐overexpressing NB cells or MYC-driven medulloblastoma cells leads to a decrease in MYCN and MYC protein levels and cell growth inhibition." (PMID 33628735, 2020). "Treatment with the PRMT5 inhibitor EPZ015666 results in a decrease of MYC protein levels and medulloblastoma cell growth, which suggests that PRMT5 inhibitors are potential therapeutics for MYC- and MYCN-driven cancers." (PMID 33628735, 2020). "The known MYC target gene, ABCE1, doesn’t show any significant co-expression correlation in Medulloblastoma." (PMID 31932624, 2020). "Therefore, miR-193a expression could be induced by MYC in the WNT subgroup medulloblastomas." (PMID 32410663, 2020). "We have identified a role for MYC in regulating the subunits of SWI/SNF in fibroblast cells and Medulloblastoma." (PMID 31932624, 2020). "Our data on PRMT5 knockdown in MYC-amplified medulloblastoma cells showed that PRMT5 can regulate the stability of MYC protein by physically interacting with it, suggesting MYC regulation by PRMT5 at the post-translation level." (PMID 31694585, 2019). "However, the role of PRMT5 and its association with MYC in medulloblastoma have not been explored." (PMID 31694585, 2019). "For this purpose, we first assessed the levels of MYC and MiT/TFE proteins in a human tumor tissue microarray derived from colon adenocarcinoma, and in patient-derived xenografts from group 3 medulloblastoma and rhabdomyosarcoma." (PMID 31399583, 2019). "To address the role of PRMT5 in medulloblastoma, we first accessed expression of PRMT5 across medulloblastoma subgroups including Group 3 medulloblastoma patients and high-MYC expressing medulloblastoma cell lines." (PMID 31694585, 2019). "We further examined the correlation between PRMT5 and MYC expression at the protein levels by western blotting in non-MYC (Daoy, ONS-76) and three MYC-driven (D-283, D-341, HD-MB-03) medulloblastoma cell lines compared to normal cerebellum." (PMID 31694585, 2019). "We first determined the growth inhibitory efficacy of EPZ015666 against three MYC-amplified (D-283, D-341, HD-MB03) and two non-MYC amplified (Daoy, ONS-76) medulloblastoma cell lines." (PMID 31694585, 2019).
medulloblastoma (continued). "According to these observations it was concluded that the interaction between MYC and MIZ1 is required for G3 medulloblastoma development; active repression by the MYC/MIZ1 complex maintains the cellular and molecular identity of G3 tumors." (PMID 30279357, 2018). "Amplification and overexpression of the MYC oncogene family, especially c-MYC and/or MYCN, have been described in medulloblastoma." (PMID 28333115, 2017). "iFISH analysis is considered the “gold-standard” for analysis of the MYC and MYCN copy number status in medulloblastomas in neuropathological practice." (PMID 27781424, 2016). "When compared to DMSO treated medulloblastoma cells, ALP treated cells showed down-regulation of genes involved in cell cycle, including MYC." (PMID 26061748, 2015). "Group 4 medulloblastomas have a higher proportion of seeding at presentation than WNT and SHH subgroups, but MYC amplification and anaplasia are seldom found in the subgroup." (PMID 23768125, 2013). "Treatment of medulloblastoma cell lines with JQ1 significantly reduced cell proliferation and preferentially induced apoptosis in cells expressing high levels of MYC." (PMID 24231268, 2013). "Here we show that selectively targeting MYC using JQ1, a small molecule inhibiting BET bromodomains, displayed broad antineoplastic effects in medulloblastoma in vitro and in vivo." (PMID 24231268, 2013). "To address the potential contribution of MYC or MYCN, we screened gene expression microarray data of 27 medulloblastoma specimens that were among 64 previously reported tumors." (PMID 16968546, 2006). "It is important to note that this treatment is specific for MYC-driven medulloblastoma but not non-MYC-amplified medulloblastoma, as PRMT5 physically interacts with and regulates MYC protein expression." (PMID 39826691, 2025). "The CDK inhibitor ribociclib inhibited MYC-driven and SHH medulloblastoma tumor progression models." (PMID 39779613, 2025). "Non-WNT/non-SHH tumours with MYC activation are the most aggressive medulloblastoma subclass, with a five-year overall survival (OS) of <60%." (PMID 41257104, 2025). "Only RCAS‐Shh or RCAS‐Shh + MYC or RCAS‐Shh + MYC T50A virus elicited medulloblastomas, whilst all other combinations resulted in no tumourigenesis." (PMID 39324445, 2024). "Our analysis of bulk RNA-seq from CT and non-CT medulloblastomas emphasised differences in gene expression and activated pathways, in particular regarding MYC driven transcription, SHH signalling, and proliferation." (PMID 39580568, 2024). "Here, we identified MYC-driven medulloblastoma as one of the most significantly affected cancer types following CDK8 depletion, demonstrating the essential role of CDK8 in driving medulloblastoma growth." (PMID 39574899, 2024). "It is indispensable for MYC-driven medulloblastoma cells, but not for non-MYC-driven medulloblastoma or other types of cancer cells." (PMID 39333489, 2024). "In comparing the transcriptome of tumors to the cells of origin and an established Sonic Hedgehog medulloblastoma model, we gathered first hints on deregulated gene expression that could be specifically involved in SMARCA4/MYC driven tumorigenesis." (PMID 37919824, 2023). "Some medulloblastoma cell lines with high MYC expression still exhibit high NE scores, indicating that c-Myc activation does not always result in the loss of NE fate." (PMID 37255415, 2023). "Nonetheless, the function of PRMT5 and its interaction with MYC in MYC-driven medulloblastoma have not been fully investigated." (PMID 38136401, 2023).
medulloblastoma (continued). "The WNT signaling may enhance glycolysis partly through the activation of MYC, although whether the link exists in WNT subgroup medulloblastomas is unknown." (PMID 37894287, 2023). "While mice overexpressing the gene combinations GFI1 + c-MYC (GM) and OTX2 + c-MYC (OM) induced brain tumors, only the latter combination developed medulloblastoma clustered with Group 3 subtype, highlighting the role of OTX2 and c-MYC as the medulloblastoma driver genes." (PMID 36831595, 2023). "In addition, we also enriched some signaling pathways that have been widely reported to affect the metastasis of medulloblastoma, such as PI3K/AKT, TGF-beta, MYC, Notch, KRAS signaling pathway." (PMID 36303547, 2022). "In addition, JQ1 has been shown to efficiently target MYC/MYCN transcription in pediatric NB and medulloblastoma." (PMID 34565342, 2021). "In human medulloblastoma cells, use of RA has been shown to induce cell growth arrest as evidenced by inhibition and decreased expression of the cell cycle markers cyclin D 1 (CYCD1) and MYC proto-oncogene bHLH transcription factor (CMYC)." (PMID 34012965, 2021). "To evaluate the mechanisms by which PLK1 is overexpressed in MYC-driven medulloblastoma, we first asked whether c-MYC activates PLK1 transcription in medulloblastoma." (PMID 33494392, 2021). "Unlike WNT- and SHH-activated medulloblastoma, the Group 3 tumors are less defined; some studies showed MYC amplification leading to tumor formation in this subgroup." (PMID 33869004, 2021). "MiR-193a is not expressed in Group 3 medulloblastomas, despite MYC expression, as a result of promoter hypermethylation." (PMID 32410663, 2020). "Importantly, the correlation coefficient of the subunit ARID2 in Medulloblastoma was found to be reversed as that in MEF and indicates the different ways of MYC dependent regulation possibilities on a gene." (PMID 31932624, 2020). "Several Group 3 medulloblastomas and the established Group 3 cell lines overexpress MYC with or without amplification of the MYC oncogene." (PMID 32410663, 2020). "MYC amplification is a well-established poor prognosticator in various risk stratification models, thus the lack of this group-specific marker in adult medulloblastoma might explain why Group 3 patients did not exhibit worse survival than the other groups in our adult cohort." (PMID 33172502, 2020). "MYC overexpression with or without amplification is a marker for poor prognosis in Group 3 medulloblastomas." (PMID 32410663, 2020). "We observed overexpression of PRMT5 in MYC-driven primary medulloblastoma tumors and cell lines compared to non-MYC medulloblastoma tumors and adjacent normal tissues." (PMID 31694585, 2019). "Our results reveal the regulation of MYC oncoprotein by PRMT5 and suggest that targeting PRMT5 could be a potential therapeutic strategy for MYC-driven medulloblastoma." (PMID 31694585, 2019). "Our results also indicated that MYC-amplified cells show greater sensitivity to EPZ015666 compared to non-MYC amplified medulloblastoma cells, further supporting the role of PRMT5 acting in MYC-dependent manner." (PMID 31694585, 2019). "We also observed a superior efficacy of this inhibitor against MYC-amplified medulloblastoma cells compared to non-MYC-amplified medulloblastoma cells, indicating specificity." (PMID 31694585, 2019). "Transactivated by HIF-1α, MYC is a prominent biological determinant in SHH (MYCN) and group 3 (MYCC) medulloblastoma but has not been widely implicated in group 4 biology, although MYCN amplifications are infrequently observed." (PMID 29880060, 2018). "In medulloblastoma, miR-219 downregulated CD164 and in consequence MYC was degraded." (PMID 30038718, 2018).
medulloblastoma (continued). "In an orthotopic xenograft model, Gfi1/Gfi1b cooperates with c-MYC to drive medulloblastoma, despite the fact that neither alone is sufficient to promote tumorigenesis." (PMID 28333115, 2017). "According to several reports, medulloblastoma is classified into four molecularly distinct subgroups –WNT, SHH, Group C (MYC activated), and Group D. Zebrafish tumors induced by rb1 somatic inactivation displayed an apparent up-regulation of genes in neural development and NOTCH pathway." (PMID 28903419, 2017). "Furthermore, somatic gene transfer of c-MYC and antiapoptoic Bcl-2 induces large cell/anaplastic (LCA) medulloblastoma in Nestin-TVA mice." (PMID 28333115, 2017). "The relationship of IGF signaling, MYC and medulloblastoma pathogenesis is not surprising given the normal developmental biology of precursors of medulloblastoma." (PMID 27255663, 2016). "The RNAseq results also indicate that GFI1 was not highly expressed and GFI1B transcripts were not present at all, indicating that GFI1 and GFI1B were not the MYC-cooperating genes in this medulloblastoma." (PMID 26380221, 2015). "In fact, increased MYC expression (without MYC copy number variation) is also found in the WNT subgroup medulloblastoma tumors with the highest survival." (PMID 25970789, 2015). "We also treated UW228 cells, another medulloblastoma cell line without 17p11.2 abnormality or MYC amplification, with lovastatin and found there was a significant induction of miR-33b and SREBF1c and a decrease in c-Myc expression." (PMID 22887866, 2012). "We performed a small-scale screening assay to identify FDA-approved compounds that reduce medulloblastoma cell viability and increase miR-33b expression using Daoy, a medulloblastoma cell line with an intact 17p11.2 and no gene amplification of MYC." (PMID 22887866, 2012). "We analyzed SREBF1 (SREBF1a and SREBF1c were not distinguishable) and MYC expression in medulloblastoma from four published reports with openly available data on genetic and gene expression profiles, pathway signatures and clinical pathological features." (PMID 22887866, 2012). "We first employed D283 Med (D283), a medulloblastoma cell line without 17p11.2 and with high levels of c-Myc, but without MYC gene amplification." (PMID 22887866, 2012). "These genes, but not the genes with single OTX2 binding or the genes with multiple OTX2 binding and no MYC, were enriched for medulloblastoma and stem cell specific genes." (PMID 22016811, 2011). "Our findings implicate hsa-miR-30b, hsa-miR-30d and KHDRBS3 as putative oncogenic target(s) of a novel recurrent medulloblastoma amplicon at 8q24.22–q24.23, which is independent of MYC amplification and unique to this disease." (PMID 19584924, 2009). "Higher levels of MYC expression correlated with slightly worse outcome among the larger group of 64 medulloblastomas, although failed to achieve statistical significance (in agreement with previous results)." (PMID 16968546, 2006). "Specifically, DIPG, ATRT (TYR, MYC), and medulloblastoma (SHH) had increased levels of CD4 expression, also known to be expressed by human monocytes and macrophages, while CD8 expression tended to be decreased, except in the case of WNT-activated medulloblastoma." (PMID 41541220, 2026). "MYC-amplified medulloblastoma has a worse outcome compared to non-MYC amplified medulloblastoma." (PMID 35267619, 2022).